GTF2F1 (general transcription factor IIF subunit 1)
Description:
TFIIF is a general transcription initiation factor that binds to RNA polymerase II and helps to recruit it to the initiation complex in collaboration with TFIIB. It promotes transcription elongation.
Synonyms: TFIIF-alpha; RAP74; TFIIF; BTF4; TF2F1
Tractability: Small molecule: a structure with a bound ligand is known. PROTAC: ubiquitination databases record sites on it; its protein half-life has been measured.
Gene: Protein-coding gene on chromosome 19 (6,379,572 to 6,393,981, reverse strand). Ensembl gene ENSG00000125651.
Subcellular location: Nucleus
Subcellular location (Human Protein Atlas): Nucleoplasm
Pathways (Reactome):
Disease: Abortive elongation of HIV-1 transcript in the absence of Tat; Dengue Virus-Host Interactions; Formation of HIV elongation complex in the absence of HIV Tat; Formation of HIV-1 elongation complex containing HIV-1 Tat; Formation of the HIV-1 Early Elongation Complex; HIV Transcription Initiation; HIV elongation arrest and recovery; Pausing and recovery of HIV elongation; Pausing and recovery of Tat-mediated HIV elongation; RNA Pol II CTD phosphorylation and interaction with CE during HIV infection; RNA Polymerase II HIV Promoter Escape; Signaling by FGFR2 IIIa TM; Tat-mediated HIV elongation arrest and recovery; Tat-mediated elongation of the HIV-1 transcript; Transcription of the HIV genome; Viral Messenger RNA Synthesis
Gene expression (Transcription): Formation of RNA Pol II elongation complex; Formation of the Early Elongation Complex; RNA Pol II CTD phosphorylation and interaction with CE; RNA Polymerase II Pre-transcription Events; RNA Polymerase II Promoter Escape; RNA Polymerase II Transcription Elongation; RNA Polymerase II Transcription Initiation; RNA Polymerase II Transcription Initiation And Promoter Clearance; RNA Polymerase II Transcription Pre-Initiation And Promoter Opening; RNA polymerase II transcribes snRNA genes
Metabolism of RNA: Processing of Capped Intron-Containing Pre-mRNA; mRNA Capping; mRNA Polyadenylation; mRNA Splicing - Major Pathway; mRNA Splicing - Minor Pathway
Signal Transduction: Estrogen-dependent gene expression; FGFR2 alternative splicing
Gene Ontology:
Molecular function: phosphatase activator activity; promoter-specific chromatin binding; protein binding; protein domain specific binding; protein phosphatase binding; RNA binding; RNA polymerase II general transcription initiation factor activity; RNA polymerase II general transcription initiation factor binding; TFIIF-class transcription factor complex binding; DNA binding
Biological process: negative regulation of protein binding; positive regulation of transcription by RNA polymerase II; response to virus; transcription elongation by RNA polymerase II; transcription initiation at RNA polymerase II promoter; transcription by RNA polymerase II; positive regulation of transcription elongation by RNA polymerase II
Cellular component: nucleoplasm; nucleus; protein-containing complex; transcription factor TFIID complex; transcription factor TFIIF complex
Genetic constraint (gnomAD): Loss-of-function variants: 37 observed, 60.69 expected, observed/expected ratio (o/e) 0.61, 90% interval 0.47 to 0.8. The upper end of that interval is the gene's LOEUF score, 0.8, which puts it in group 3 of 6, group 1 being the genes least tolerant of losing a copy. Missense variants: 628 observed, 701.01 expected, observed/expected ratio (o/e) 0.9, 90% interval 0.84 to 0.96. Synonymous variants: 273 observed, 282.39 expected, observed/expected ratio (o/e) 0.97, 90% interval 0.88 to 1.07.
Homologues: Orthologues: chimpanzee GTF2F1 (99% identical), pig GTF2F1 (94% identical), dog GTF2F1 (94% identical), guinea pig GTF2F1 (94% identical), mouse Gtf2f1 (91% identical), rat Gtf2f1 (91% identical), tropical clawed frog gtf2f1 (75% identical), zebrafish gtf2f1 (71% identical), Drosophila melanogaster TfIIFalpha (44% identical), Caenorhabditis elegans gtf-2F1 (31% identical).
Diseases named in the same sentence as GTF2F1 in open-access papers:
GTF2F1 is named in the same sentence as 2 diseases in open-access papers, as found by Europe PMC text mining. Sharing a sentence is not in itself a finding about the gene and the disease. The quoted sentences say what the papers report.
enterovirus infection (1 paper, 2019). "In turn, the GTF2F1 gene demonstrated upregulation in response to enterovirus infection." (PMID 31185018, 2019).
infection (2 papers, 2020 to 2025). The state of being infected such as from the introduction of a foreign agent such as serum, vaccine, antigenic substance or organism. "Interestingly, several unexpected kinases were identified at the earliest timepoints, including GTF2F1 and Aurora, suggesting that these may regulate previously unrecognized pathways that underlie macrophage responses to infection." (PMID 31951200, 2020). "While STAT3's role in Theileria infections is well-established, the functions of the others (GTF2F1 and NFATC1) remain unclear." (PMID 40368139, 2025). "Notably, 12 of these TFs exhibited distinct phosphorylation patterns upon infection, including MED14, SIN3A, BCL6, cJUN, NFATC1, STAT3, RUNX3, GTF2F1, MED1, JUNB, TLE3, and FOSL2." (PMID 40368139, 2025).